INS (insulin)
Diseases named in the same sentence as INS in open-access papers (continued):
Sharing a sentence is not in itself a finding about the gene and the disease.
Insulin resistance (continued). "Skeletal muscle is the primary site for insulin-mediated glucose uptake via glucose transporter type 4 (GLUT4), and reduced muscle function contributes to insulin resistance and metabolic dysfunction." (PMID 40870518, 2025). "Clinical trials, including a large-scale RCT (n = 535), have demonstrated that chiglitazar sodium effectively reduces HbA1c, improves fasting plasma insulin, and enhances measures of β-cell function (HOMA-β) and insulin resistance (HOMA-IR)." (PMID 41427055, 2025). "In mice with diet-induced insulin resistance, Usp25m abundance is reduced, IRAP is mislocalized during fasting, and TUG cleavage is impaired; effects of Usp25m and TUG deletion to alter insulin-stimulated and fasting glucose uptake, respectively, are ablated." (PMID 40631311, 2025). "Oleate administration effectively restored the insulin-stimulated translocation of GLUT4 and the phosphorylation of AS160 and Akt-2, suggesting a protective effect against palmitate-induced insulin resistance." (PMID 39940428, 2025). "Body glucose homeostasis was evaluated with the indices of Fasting Blood Sugar (FBS), Hemoglobin A1c (HbA1c), Fasting Plasma Insulin (FPI), and calculation of the Homeostasis Model Assessment of Insulin Resistance (HOMA-IR)." (PMID 41517125, 2025). "The crosstalk between NF-κB and c-Jun N-terminal kinase (JNK) pathways further amplifies insulin resistance, particularly through phosphorylation of insulin receptor substrate-1 (IRS-1), thereby impairing insulin signal transduction." (PMID 40868165, 2025). "The development of a nongenetic model for T2D typically involves the initial induction of insulin resistance through a high-fat diet (HFD), followed by partial β-cell dysfunction that impairs insulin secretion." (PMID 41002949, 2025). "Insulin has also been shown to stimulate testosterone production in adipose tissue through aldoketoredutase type 3 (AKR1C3) elevation and insulin resistance in women." (PMID 40410881, 2025). "At week 24, the treatment group had lower fasting blood glucose (p < 0.02) and improved insulin sensitivity (QUICKI, p = 0.02), and indicated a trend toward lower insulin resistance (HOMA-IR, p = 0.05) compared with the control." (PMID 40941087, 2025). "As anticipated, the DOB group displayed the poorest metabolic profile, characterized by elevated fasting glucose, insulin, HbA1c, and HOMA-IR, indicating significant metabolic dysfunction and insulin resistance." (PMID 41228453, 2025). "In the control group, 64.7% had insulin resistance (IR) according to HOMA-IR, while 44.4% met the ISI Matsuda criterion for IR, showing a significant difference in peripheral insulin sensitivity between groups." (PMID 40075777, 2025). "This review discusses the relationships between bilirubin, HMOX, and insulin sensitivity, how T2DM medications affect HMOX levels and activity, and potentially using bilirubin nanoparticles to treat insulin resistance." (PMID 39873298, 2025). "In the subcutaneous adipose tissue depot, gene expression of DSP and GJA1 was negatively correlated with Homeostatic Model Assessment for Insulin Resistance (HOMA-IR), indicating at a potential role in insulin sensitivity." (PMID 41275133, 2025). "Muscle‐specific GLUT4 knockout mice developed severe insulin resistance and glucose intolerance, while adipose‐specific GLUT4 knockout mice showed impaired insulin responses in both the liver and muscle." (PMID 40522008, 2025). "The homeostasis model assessment of insulin resistance (HOMA-IR) and quantitative insulin sensitivity check index (QUICKI) are both surrogate indices of insulin resistance that are mathematically derived from fasting glucose and insulin levels." (PMID 40013621, 2025). "During network meta-analysis, Moxibustion combined with catgut embedding was the most effective measure in the improvement of FPG, fasting insulin (FIN) and insulin resistance (IR)." (PMID 40527787, 2025).
Insulin resistance (continued). "Metformin can improve metabolic insulin resistance, while glucagon-like peptide-1 receptor agonists (GLP-1RAs) have the ability to stimulate insulin release." (PMID 41020901, 2025). "Thus, these works were addressed to elucidate the signaling pathways by which FFARs mediate the effects of fatty acids on insulin secretion and lipotoxicity, which may lead to new therapeutic strategies for managing insulin resistance and related metabolic disorders." (PMID 39859502, 2025). "A study on kidney transplant patients demonstrated that patients with higher insulin resistance and an IGR (insulin-to-glucose ratio) ≥ 0.092 experienced worse early graft function." (PMID 39941214, 2025). "During the development of insulin resistance, the proportion of FLTP-low cells increases, accompanied by reduced insulin secretion." (PMID 41584842, 2025). "We observed that MUSTN1-KO enhanced glucose tolerance and insulin sensitivity in mice fed an HFD, protecting against HFD-induced insulin resistance." (PMID 40239869, 2025). "Indicators frequently employed to evaluate insulin sensitivity include fasting blood glucose (FBG), fasting blood insulin (FBI), homeostasis model assessment of insulin resistance (HOMA-IR), and oral glucose tolerance testing." (PMID 41003008, 2025). "Elevated ROCK1 activity contributes to insulin resistance, and its inhibition, as seen in our treatment groups, has been shown to improve insulin sensitivity and directly promote GLUT4 translocation in insulin-responsive tissues." (PMID 40954151, 2025). "Numerous indices of insulin resistance were also calculated, such as HOMA-IR, insulin sensitivity index (QUICKI), fasting glucose-to-insulin ratio (FGIR) and whole-body insulin sensitivity index (ISI)." (PMID 40491594, 2025). "Overall, these results reinforce the central role of insulin resistance in NAFLD development and highlight the potential of early insulin sensitization to significantly mitigate the hepatometabolic risks associated with increased body fat." (PMID 40640543, 2025). "Mean difference in fasting blood glucose, insulin resistance (HOMA-IR), and fasting insulin levels per 1-unit increase in dietary selenium intake (μg/1000 kcal) in Saudi adults (n=1074)a." (PMID 40519519, 2025). "Within the European Group for Insulin Resistance Research (EGIR), insulin sensitivity, as measured by the hyperinsulinemic-euglycemic clamp method, showed a strong correlation with triglyceride (TG) levels." (PMID 40421238, 2025). "The chronic inflammation interferes with insulin signaling through cytokines, such as Tumor necrosis factor-α and Interleukin- 6(TNF-α and IL-6), and inhibits adipocyte differentiation, leading to insulin resistance and lipid accumulation." (PMID 41019065, 2025). "Insulin resistance, a feature of chronic kidney disease (CKD), disrupts the insulin signaling cascade." (PMID 40698245, 2025). "Age-related defects in insulin signaling cascades, such as reduced insulin-stimulated tyrosine phosphorylation, are more pronounced in adipose tissue than in liver or muscle, suggesting that adipose tissue may be central to the development of insulin resistance with aging." (PMID 41357171, 2025). "Omega-3 fatty acids enhance insulin sensitivity through PPAR-γ activation and anti-inflammatory effects, whereas excessive omega-6 intake promotes insulin resistance via inflammation, dysregulated adipokine release, and ER stress induction." (PMID 40362254, 2025). "Insulin resistance (IR) is the fundamental pathological mechanism of T2DM, as reduced insulin action in adipose tissue leads to increased free fatty acid (FFA) release, which exacerbates insulin resistance." (PMID 39920728, 2025). "The fasting plasma glucose (FPG), fasting plasma insulin (FPI), and HOMA-IR levels in the T2DM macaques were significantly higher than in the control group (p<0.01), suggesting insulin resistance in T2DM macaques." (PMID 40878918, 2025).
Insulin resistance (continued). "As ISOGTT is a parameter of insulin sensitivity, the ISOGTT in the high and middle adipose tissue insulin resistance (ATIR) groups was significantly lower than that in the low ATIR group in young, healthy, non-pregnant Japanese women." (PMID 39940296, 2025). "Inhibition of the Gbb pathway ameliorated HFD-induced metabolic phenotypes by promoting insulin resistance, mediated by increasing the expression of the tribbles gene (TRB3), a key inhibitor of insulin signaling." (PMID 40260391, 2025). "Insulin resistance is a key characteristic of MASLD and is characterized by diminished insulin sensitivity in the whole body, including the liver, skeletal muscle, and adipose tissues." (PMID 40564877, 2025). "Under normal circumstances, insulin can induce glucose transporter type 4 (GLUT4) transfer to the plasma membrane, and FTO over-expression inhibits GLUT4 transport induced by insulin in KGN cells, resulting in insulin resistance." (PMID 40410881, 2025). "This inclusion links peripheral insulin resistance with hepatic insulin resistance, and the generated HGP-insulin dose-response curve aligns well with experimental observations." (PMID 40568093, 2025). "In a dexamethasone-induced obesity-related insulin resistance model, DHM significantly increases adipocyte insulin sensitivity by inhibiting ERK-mediated phosphorylation of the PPARγ serine 273 site, promotes glucose uptake, and reduces lipid accumulation." (PMID 40740995, 2025). "Il1b is known to disrupt insulin signaling pathways by activating NF-κB and reducing insulin receptor substrate (IRS) phosphorylation, thereby contributing to systemic insulin resistance." (PMID 41019552, 2025). "In this study, obese mice exhibited significantly increased fasting blood glucose and insulin levels and a HOMA-IR index, while the HOMA-IS index and glucose tolerance were significantly reduced, indicating a state of insulin resistance." (PMID 39942052, 2025). "Insulin (M = 9.91 vs. 7.27, p = 0.003) and HOMA-IR (M = 2.28 vs. 1.52, p = 0.004) findings indicate insulin resistance, which can guide lifestyle interventions or metformin therapy to prevent metabolic complications." (PMID 41220482, 2025). "This cytokine, secreted by regulatory T lymphocytes, has anti-inflammatory effects, increasing insulin sensitivity and opposing the role of tumor necrosis factor (TNF)-α in inducing insulin resistance in 3T3L adipocytes." (PMID 41259454, 2025). "The glucose/insulin ratio (GIR), homeostatic model assessment for insulin resistance (HOMA-IR), and quantitative insulin sensitivity check index (QUICKI) were used to assess insulin sensitivity." (PMID 40573153, 2025). "In obesity, insulin resistance, and T2DM, adiponectin levels are significantly decreased, resulting in reduced insulin sensitivity, glucose uptake, and fatty acid metabolism." (PMID 40722840, 2025). "Spearman correlation between dietary selenium intake and fasting blood glucose, insulin resistance (HOMA-IR), and fasting insulin levels in Saudi adults (n=1074)a." (PMID 40519519, 2025). "In metabolic diseases such as insulin resistance and obesity, the expression level of GPX1 has a significant impact on insulin signaling pathways." (PMID 40599237, 2025). "Mechanistically, they showed that PAR2 activation inhibited insulin-Akt signalling, promoting insulin resistance, whereas pharmacological inhibition or genetic silencing of PAR2 restored insulin sensitivity." (PMID 40806209, 2025). "In this study, HFD-fed rats exhibited markedly elevated serum insulin levels and increased FBG concentrations, indicative of insulin resistance and glucose intolerance—hallmarks of metabolic syndrome and T2DM." (PMID 40867531, 2025). "The combination of running and anaerobic exercise demonstrated superior efficacy in alleviating insulin resistance, as supported by a significant reduction in the HOMA-IR index, indicating an enhanced improvement in insulin sensitivity." (PMID 40951419, 2025).
Insulin resistance (continued). "Among the most widely accepted surrogate markers are the triglyceride-glucose index (TyG), its variant incorporating body mass index (TyG-BMI), the metabolic score for insulin resistance (METS-IR), and the single point insulin sensitivity estimator (SPISE)." (PMID 40648978, 2025). "In contrast, NCD-fed CST-KO mice displayed insulin resistance, suggesting that CST plays an insulin-sensitizing role." (PMID 41298823, 2025). "However, insulin initiation may be delayed because of psychological insulin resistance (PIR)." (PMID 40336418, 2025). "Fasting insulin levels were elevated in seven individuals, with a mean of 14.96 ± 11.32 mU/L (reference: 2.6–24.9 mU/L), and HOMA-IR index of insulin resistance in 33 subjects with a median value of 3.35 (2.48; 4.38) (reference < 2.32)." (PMID 40943919, 2025). "Since hyperinsulinemia is believed to be a precursor to insulin resistance, and insulin resistance is a key component in the pathogenesis of type 2 diabetes, we utilized the HOMA‐IR formula and the insulin sensitivity index (ISI0,120) for further analysis." (PMID 39821966, 2025). "The markers of insulin resistance (HOMA-IR) were higher in the diabetic patients (7.3 vs. 3.2, p = 0.017), while the insulin sensitivity (HOMA-IS and QUICKI) was significantly lower (both p = 0.017)." (PMID 40217596, 2025). "Testosterone correlated negatively with age, obesity markers (eg, BMI, WHR, body fat percentage), and markers of insulin resistance and hyperglycemia (eg, HbA1c, HOMA-IR, serum insulin)." (PMID 39833659, 2025). "Intriguingly, these compounds exhibit hypoglycemic potential: Eriodictyol enhances glucose uptake and ameliorates insulin resistance via PI3K/AKT-mediated AKT phosphorylation and stimulates insulin secretion through the cAMP/PKA pathway." (PMID 40647154, 2025). "The improvement of homeostasis model assessment of beta-cell function (HOMA-β), Fasting Insulin (FINS), and HOMA insulin resistance (HOMA-IR) in the TCM group was better than the traditional group (P<0.05)." (PMID 40621543, 2025). "Several trials report reductions in fasting insulin levels and HOMA-IR (Homeostasis Model Assessment of Insulin Resistance) in resveratrol-treated patients." (PMID 40563357, 2025). "High sUA levels impair insulin signaling through inhibition of intrahepatic IRS1 and Akt pathways, thereby inducing insulin resistance." (PMID 40089555, 2025). "Both insulin resistance as determined by homeostasis model assessment of β-cell function (SMD = −0.68, 95% CI: −1.00 to −0.36) and fasting insulin levels were significantly lower (SMD = −0.58, 95% CI: −0.90 to −0.26)." (PMID 41141267, 2025). "Consistently, the homeostatic model assessment of insulin resistance (HOMA-IR) was significantly reduced in the tryptamine-supplemented group compared to the control groups, indicating improved whole-body insulin sensitivity." (PMID 39941095, 2025). "TNF-α directly impairs insulin signalling by increasing serine phosphorylation of insulin receptor substrates (IRS), promoting insulin resistance." (PMID 40700071, 2025). "ABE has been shown to attenuate insulin resistance, an age-related disorder, by inhibiting the pro-inflammatory cytokine TNF-α, which in turn increased insulin-stimulated glucose uptake in adipocytes." (PMID 40565158, 2025). "Studies have demonstrated that excessive insulin can induce granulosa cell apoptosis and activate the AKT/mTOR pathway, suggesting a close relationship between the mTOR pathway and insulin resistance in PCOS." (PMID 40937413, 2025). "For instance, when rat skeletal muscle myotubes are exposed to testosterone for 16 h, they exhibit increased insulin-induced serine phosphorylation of IRS-1, which is thought to uncouple IRS-1 signal transduction to PI3K, and thus result in insulin resistance." (PMID 40013621, 2025). "Changes in insulin signaling pathways, such as insulin receptors and substrates, MAPK, JNK, PI3K, AKT, and mTOR, contribute to insulin resistance in GDM." (PMID 40453589, 2025).
Insulin resistance (continued). "In addition, chronic high-dose exogenous insulin therapy may further promote insulin resistance." (PMID 41257477, 2025). "We had data about the baseline insulin for a limited number of patients, which prevented to determine the homeostasis model assessment of β-cell function (HOMA-β) and of insulin resistance (HOMA-IR) indexes." (PMID 40075815, 2025). "As the expression of PKDkd increased glucose sensitivity and decreased insulin resistance in a HFD model, we tested if pharmacological PKD inhibition would be beneficial in an already existing HFD-induced insulin and glucose intolerance setting as well." (PMID 41349796, 2025). "In summary, the patients with HS showed significantly higher fasting insulin levels, increased insulin resistance (HOMA-IR), and reduced insulin sensitivity (SPINA-GR) compared to the controls." (PMID 40217596, 2025). "In PLH, patients with high HOMA-βlevels were characterized by high insulin resistance, as indicated by high HOMA-IR, fasting insulin, body fat mass, WC, BMI, and TG, and low LPL and HDL-C." (PMID 41156460, 2025). "Fasting measures of insulin resistance [HOMA IR, HOMA-β and fasting insulin] reduced in the CER group and with IER when assessed immediately after the two low energy days but were not maintained during normal eating days." (PMID 41146360, 2025). "Insulin resistance not only exacerbates hyperinsulinemia but also promotes Aβ accumulation, due in part to the competitive role of IDE, which degrades both insulin and Aβ." (PMID 40724942, 2025). "Insulin resistance is commonly assessed using the Homeostasis Model of Assessment for Insulin Resistance (HOMA-IR), calculated from fasting glucose and insulin levels." (PMID 40509433, 2025). "This implies that potential impairments in insulin resistance in Rwanda during early or mid-pregnancy may have subsequently led to the significantly elevated glucose concentrations observed during the later stage of pregnancy, when compensatory insulin production by beta cells becomes insufficient." (PMID 40643164, 2025). "In adipose tissue, insulin resistance leads to enhanced lipolysis and elevated plasma free fatty acid (FFA), which further impair insulin sensitivity in muscle and liver and contribute to hepatic dysfunction of β cells." (PMID 41012462, 2025). "In conditions associated with inflammation (a common occurrence in cases of obesity and insulin resistance), the reduction in inflammatory cytokines (e.g., TNF-α, IL-6) that hinder insulin action can be attributed to SCFA production." (PMID 40650200, 2025). "Insulin resistance markers were assessed during the recent visit in young adulthood, including the homeostatic model assessment of insulin resistance (HOMA-IR; calculated from fasting glucose and insulin levels) and glycated hemoglobin (HbA1c) level." (PMID 40261649, 2025). "Insulin resistance, as shown by elevated FBG and serum insulin, was effectively ameliorated by CGA, particularly at the higher dose." (PMID 40867531, 2025). "This is further supported by elevated insulin levels in the T2D group compared to NPD group, suggesting insulin resistance, as the high glucose concentrations reflect defects in insulin secretion, action, or both." (PMID 40650008, 2025). "On the contrary, the HFD+K mice had plasma glucose and insulin concentration significantly lower than HFD mice and presented a clear improvement of insulin resistance as showed by the significantly reduced HOMA-IR." (PMID 40243721, 2025). "The essential point in the connection of insulin resistance (as an outcome of PCOS) and acne is that overproduction of insulin leads to increasing levels of insulin-like growth factor 1 (IGF-1)." (PMID 41473651, 2025). "Traditional methods for assessing insulin resistance, such as the Homeostatic Model Assessment for Insulin Resistance (HOMA-IR), rely on measurements of fasting insulin levels." (PMID 41180178, 2025).